RN7SL7P (RNA, 7SL, cytoplasmic 7, pseudogene)
Synonyms: 7L23; formerly RN7SLP4; RN7SL27P
Gene: Miscellaneous RNA gene on chromosome 7 (92,971,002 to 92,971,299, reverse strand). Ensembl gene ENSG00000266794.
Homologues: Orthologues: chimpanzee Metazoa_SRP (97% identical), macaque Metazoa_SRP (92% identical). Paralogues in human: RN7SL1 (88% identical), RN7SL2 (88% identical), RN7SL3 (86% identical), RN7SL45P (84% identical), RN7SL296P (83% identical), RN7SL126P (82% identical), RN7SL230P (82% identical), RN7SL748P (82% identical), Metazoa_SRP (82% identical), RN7SL118P (82% identical), RN7SL627P (82% identical), RN7SL652P (82% identical), and 704 more.